USP32P1 (ubiquitin specific peptidase 32 pseudogene 1)
Gene: Transcribed unprocessed pseudogene on chromosome 17 (16,796,043 to 16,802,427, forward strand). Ensembl gene ENSG00000188933.
Diseases named in the same sentence as USP32P1 in open-access papers:
USP32P1 is named in the same sentence as 2 diseases in open-access papers, as found by Europe PMC text mining. Sharing a sentence is not in itself a finding about the gene and the disease.
USP32P1 shares sentences with these, for which no sentence is quoted: autosomal dominant polycystic kidney disease (1 paper); pancreatic adenocarcinoma (1).